SLC30A9 (solute carrier family 30 member 9)
Description:
Mitochondrial proton-coupled zinc ion antiporter mediating the export of zinc from the mitochondria and involved in zinc homeostasis, zinc mobilization as well as mitochondrial morphology and health. In nucleus, functions as a secondary coactivator for nuclear receptors by cooperating with p160 coactivators subtypes. Plays a role in transcriptional activation of Wnt-responsive genes (By similarity).
Synonyms: HuEL; C4orf1; ZNT9; GAC63; BILAPES
Tractability: Antibody: UniProt predicts a signal peptide or a membrane-spanning region. PROTAC: ubiquitination databases record sites on it; its protein half-life has been measured.
Safety:
Unwanted effects reported when the protein is acted on. In parentheses: how it was acted on, where the effect was seen, and who reports it.
asthma (source: ClinPGx)
Gene: Protein-coding gene on chromosome 4 (41,990,496 to 42,090,461, forward strand). Ensembl gene ENSG00000014824.
Subcellular location: Mitochondrion membrane; Nucleus; Endoplasmic reticulum
Subcellular location (Human Protein Atlas): Mitochondria; Cytosol
Gene Ontology:
Molecular function: zinc ion transmembrane transporter activity; zinc:proton antiporter activity; chromatin binding; monoatomic cation transmembrane transporter activity; nuclear receptor binding; transcription coactivator activity
Biological process: intracellular zinc ion homeostasis; regulation of mitochondrion organization; zinc ion transport; nucleotide-excision repair; monoatomic cation transmembrane transport; monoatomic cation transport; positive regulation of DNA-templated transcription; transmembrane transport; zinc ion transmembrane transport
Cellular component: cytoplasmic vesicle; cytoskeleton; endoplasmic reticulum; mitochondrial membrane; mitochondrion; nucleus; membrane
Genetic constraint (gnomAD): Loss-of-function variants: 9 observed, 26.78 expected, observed/expected ratio (o/e) 0.34, 90% interval 0.2 to 0.59. The upper end of that interval is the gene's LOEUF score, 0.59, which puts it in group 2 of 6, group 1 being the genes least tolerant of losing a copy. Missense variants: 232 observed, 275.44 expected, observed/expected ratio (o/e) 0.84, 90% interval 0.76 to 0.94. Synonymous variants: 111 observed, 107.98 expected, observed/expected ratio (o/e) 1.03, 90% interval 0.88 to 1.2.
Gene-disease validity (ClinGen):
ClinGen rates the evidence that SLC30A9 causes each of these diseases.
psychomotor regression-oculomotor apraxia-movement disorder-nephropathy syndrome (autosomal recessive): Definitive.
Homologues: Orthologues: chimpanzee SLC30A9 (98% identical), macaque SLC30A9 (98% identical), rabbit SLC30A9 (95% identical), pig SLC30A9 (95% identical), mouse Slc30a9 (89% identical), guinea pig SLC30A9 (89% identical), rat Slc30a9 (89% identical), dog SLC30A9 (86% identical), tropical clawed frog slc30a9 (73% identical), zebrafish slc30a9 (73% identical), Drosophila melanogaster ZnT49B (46% identical), Caenorhabditis elegans slc-30A9 (36% identical).